SEMA3B (semaphorin 3B)
Diseases named in the same sentence as SEMA3B in open-access papers (continued):
Sharing a sentence is not in itself a finding about the gene and the disease.
rheumatoid arthritis (2 papers, 2022 to 2024). A chronic, systemic autoimmune disorder characterized by inflammation in the synovial membranes and articular surfaces. "Further, Nrp1 activation by another Semaphorin 3 protein (Sema3B) has been found to promote pro-resolving polarization in macrophages from rheumatoid arthritis patients." (PMID 39234267, 2024). "Reduced levels of SEMA3B in fibroblast-like synoviocytes was found in patients with rheumatoid arthritis, suggesting a role also in the development of autoinflammatory disease." (PMID 35173190, 2022).
colon cancers (1 paper, 2015). "Suppression in transcriptional activity of this gene in tumors indicate that SEMA3B may participate in cell growth suppression in the kidney, ovary, and colon cancers." (PMID 26197878, 2015).
depression (1 paper, 2023). "Semaphorin 3B in the hippocampus may play a role in inducing depression-like behaviors." (PMID 37035502, 2023). "Increasing the levels of SEMA3B in the hippocampus or the lateral ventricles, improved CMS-induced depression-like behaviors and increased resilience to acute stress by increasing dendritic spine density in hippocampal neurons." (PMID 37035502, 2023).
endometrial cancer (1 paper, 2023). Primary or metastatic malignant neoplasm involving the endometrium (mucous membrane that lines the endometrial cavity). "In addition, cisplatin could restore the homeostasis of endometrial cancer cells and improve the effectiveness of pharmacotherapy by increasing the expression of SEMA3B in vitro." (PMID 36793711, 2023).
epilepsy (1 paper, 2022). A brain disorder characterized by episodes of abnormally increased neuronal discharge resulting in transient episodes of sensory or motor neurological dysfunction, or psychic dysfunction. "The chromosome 3 region spans 159 genes, including neuronal development genes SEMA3F and SEMA3B, and epilepsy-associated genes NPRL2, CACNA2D2, and CYB561D2." (PMID 35190550, 2022).
hematoma (1 paper, 2026). A hematoma is a collection of blood from a vascular structure into an extravascular space. "Furthermore, Sema3B enhances the interaction between PlexinA1 and TREM2, cooperatively boosting microglial phagocytosis of the hematoma after ICH." (PMID 41750601, 2026).
idiopathic pulmonary fibrosis (1 paper, 2024). Idiopathic pulmonary fibrosis (IPF) is a nonneoplastic pulmonary disease that is characterized by the formation of scar tissue within the lungs in the absence of any known cause. "SEMA3B functions as an inhibitor of transforming growth factor-β-driven fibroblast activation and reduced levels of SEMA3B and its receptor, neuropilin 1, are associated with decreased lung function in idiopathic pulmonary fibrosis." (PMID 38646784, 2024). "This study unveils an antifibrotic role for semaphorin class 3B (SEMA3B) in the pathogenesis of idiopathic pulmonary fibrosis." (PMID 38646784, 2024). "This study investigated the role of SEMA3B signaling in the pathogenesis of idiopathic pulmonary fibrosis." (PMID 38646784, 2024).
leukemia (1 paper, 2019). A malignant (clonal) hematologic disorder, involving hematopoietic stem cells and characterized by the presence of primitive or atypical myeloid or lymphoid cells in the bone marrow and the blood. "The expression levels and functional activities of SEMA3B, SEMA3F, and Neuropilin-2 have furthermore been investigated in leukemias and lymphoma cells." (PMID 31143707, 2019).
lung adenocarcinoma (1 paper, 2024). A carcinoma that arises from the lung and is characterized by the presence of malignant glandular epithelial cells. "Published studies show hypermethylation of the promotor region and gene silencing as a potential mechanism underlying the repression of the SEMA3B expression in most malignancies, including lung adenocarcinoma." (PMID 38646784, 2024).
lupus (1 paper, 2021). "After withdrawing the 18 cases of lupus, which is the most frequent cause of MN in this age range, the real prevalence of Sema3B-associated disease among non-lupus patients was 15%, thus making Sema3B the first antigen in pediatric MN." (PMID 33562791, 2021).
lymph node metastases (1 paper, 2015). "Moreover, we showed a clear difference (P < 0.05) of the SEMA3B relative mRNA levels in ADC with and without lymph node metastases." (PMID 25961819, 2015).
neuroblastoma (1 paper, 2015). Neuroblastoma (NB) is the most common solid, extracranial childhood tumor. "SEMA3B methylation has been observed in various types of cancer, including lung, liver, gallbladder, gastric, breast and oral carcinomas, and neuroblastoma." (PMID 25961819, 2015).
Osteopenia (1 paper, 2016). Osteopenia is a term to define bone density that is not normal but also not as low as osteoporosis. "Indeed, it is now known that Semaphorin 3B promotes osteoclastogenesis and osteopenia in a mouse model and that Semaphorin 3A exerts an osteoprotective effect by suppressing bone resorption and increasing bone formation." (PMID 26910109, 2016).
pancreatic cancer (1 paper, 2020). "Semaphorin signaling seems to play an important role in the development of pancreatic cancer, with a high frequency of mutations in SEMA3A and SEMA3B." (PMID 32520974, 2020).
pulmonary fibrosis (1 paper, 2024). Chronic progressive interstitial lung disorder characterized by the replacement of the lung tissue by connective tissue, leading to progressive dyspnea, respiratory failure, or right heart failure. "To determine the role of the SEMA3B-NRP1 axis in preclinical mouse models of pulmonary fibrosis, we quantified the expression of SEMA3B and NRP1 in the lungs of mice with severe fibrotic lung disease in two murine models of pulmonary fibrosis, bleomycin (BLM)-induced, and TGFα-induced lung fibrosis." (PMID 38646784, 2024). "Although studies have investigated the role of SEMA3 proteins in multiple disease conditions, the role of the SEMA3B-NRP axis in pulmonary fibrosis remains unknown." (PMID 38646784, 2024). "Therefore, it is possible that these profibrotic factors can interfere with the binding of SEMA3B to NRP1 during pulmonary fibrosis development." (PMID 38646784, 2024). "The decreased expression of SEMA3B is not limited to IPF, we observed reduced expression of SEMA3B and NRP1 in two alternative mouse models of pulmonary fibrosis." (PMID 38646784, 2024). "In this study, we investigated the expression of SEMA3B in the lungs of IPF patients and murine models of pulmonary fibrosis and determined its potential role in the pathogenesis of pulmonary fibrosis." (PMID 38646784, 2024). "Overall, our new findings highlight an antifibrotic role for SEMA3B and support modulating the SEMA3B-NRP1 axis as an innovative therapeutic approach to inhibit pulmonary fibrosis." (PMID 38646784, 2024). "The downregulation of SEMA3B and NRP1 transcripts was validated in the lung tissues of patients with IPF, and two alternative mouse models of pulmonary fibrosis." (PMID 38646784, 2024). "Overall, our findings uncovered a novel role of SEMA3B in the pathogenesis of pulmonary fibrosis and provided novel insights into modulating the SEMA3B-NRP1 axis to attenuate pulmonary fibrosis." (PMID 38646784, 2024). "Overall, our new findings highlight a potential antifibrotic role for SEMA3B and support modulating the SEMA3B-NRP1 axis as an innovative therapeutic approach to inhibit pulmonary fibrosis." (PMID 38646784, 2024). "Therefore, future studies are warranted to investigate how SEMA3B is downregulated by TGFβ signaling and potential microRNAs in IPF fibroblasts and also the mouse models of pulmonary fibrosis in vivo." (PMID 38646784, 2024).
tumor (60 papers, 2004 to 2026). "A previous study identified SEMA3B as a renal tumor suppressor gene, whose downregulation was positively associated with tumor progression, stage, and grade of ccRCC." (PMID 36353536, 2022). "Sema3B, as a potential tumor suppressor gene, gene loss or down-regulation of its function can promote tumor progressions, such as in lung cancer, breast cancer, ovarian cancer, liver cancer, and cholangiocarcinoma." (PMID 36713527, 2022). "TSPX overexpression in LNCaP cells and TSPX-high clinical prostate specimens are associated with elevated expression levels of two tumor suppressors SEMA3B and BTG2." (PMID 30863497, 2019). "The methylation analysis revealed a significant association of SEMA3B hypermethylation with tumor progression in terms of tumor stage and grade for both subtypes of NSCLC (SCC and ADC) and ccRCC." (PMID 25961819, 2015). "In this study, using PI-FACS we have shown that tumor growth suppression by SEMA3B is associated with induction of apoptosis in vitro." (PMID 25961819, 2015). "The expression of SEMA3B by cancer cells has been shown to recruit tumor-associated macrophages (TAMs) into the tumor microenvironment by the activation of a neuropilin-mediated signaling pathway that leads to an autocrine release of IL-8, thereby promoting cancer progression." (PMID 35440004, 2022). "Association of SEMA3B hypermethylation and down-regulation with tumor progression could serve as prognostic markers." (PMID 25961819, 2015). "Sema3B and Sema3F act as tumor suppressors in some cancers by suppressing tumorigenesis in certain adenocarcinoma cell lines." (PMID 40277760, 2025). "Sema3F and Sema3B act as tumor suppressors, whereas Sema3F and Sema3B are involved in cancer progression." (PMID 40277760, 2025). "Deletion or repression of SEMA3B has been observed in various cancers, including lung carcinoma, where its reexpression inhibits tumor cell growth." (PMID 38646784, 2024). "Semaphorin class 3B (SEMA3B), a secreted protein highly expressed in lung tissues, has established roles in axonal guidance and tumor suppression." (PMID 38646784, 2024). "SEMA3A and SEMA3B not only suppress tumor angiogenesis but also regulate immune cells in TME, including tumor-associated macrophages (TAMs)." (PMID 36942388, 2023). "Hypermethylation of SEMA3B gene promoter region results in decreased SEMA3B expression, which can compromise its tumor-suppressive functions, promote tumor growth, and potentially contribute to metastasis." (PMID 38001653, 2023). "As for the two tumor suppressors Lrrc4 and Sema3b, they were rich in the axon guidance signaling pathway." (PMID 37056757, 2023). "Previous studies showed that SEMA3B is characterized as a strong tumor-suppressing factor in various cancers." (PMID 36793711, 2023). "For example, several SEMA3s (e.g. SEMA3A and SEMA3B) act as inhibitors of tumor progression, whereas SEMA3C exhibits both anti- and pro- tumorigenic effects." (PMID 36942388, 2023). "Several class-3 semaphorins such as sema3A, sema3B and sema3F have been found to function as potent inhibitors of tumor angiogenesis and consequently as inhibitors of tumor progression." (PMID 36658114, 2023). "The expression level of Sema3B in PC tissues is closely related to the PC tumor stage, local invasion, lymphatic metastasis, and distant metastasis, and the expression level of Sema3B in PC tissues is closely related to the degree of malignancy of PC." (PMID 36713527, 2022). "Existing studies have suggested that Sema3B was down-regulated in tumor tissues of patients with hepatocellular carcinoma and exerts anti-motility and anti-invasion effects on tumor cells." (PMID 36016931, 2022).
tumor (continued). "In lung cancer, a loss of two chromosome regions containing semaphorins 3p21.3 (SEMA3B and SEMA3F) and 5q21–22 (SEMA6A) is associated with the inhibition of proliferation and invasion of tumor cells and angiogenesis." (PMID 34209679, 2021). "Among the tumor specimens with IDH mutation, mRNA levels of SEMA3B, SEMA3C, SEMA3D, SEMA3G, NRP2, PLXNA2, and CDH1 were significantly higher (p < 0.05), while SEMA3F, NRP1, ITGB3, ITGA5, and VEGFA genes were under-expressed (p < 0.05)." (PMID 33036421, 2020). "All other SEMA3 family members show inconsistent up- or down-regulation in different cancer tumours, where SEMA3B, SEMA3D, SEMA3E, and SEMA3G are primarily down-regulated, and SEMA3A and SEMA3C are mainly up-regulated in the tested cancer types." (PMID 32241267, 2020). "Whereas SEMA3A, SEMA3C, and SEMA3F were mainly up-regulated in the tested tumours, the rest of the members SEMA3B, SEMA3D, SEMA3E and SEMA3G were primarily down-regulated with a few exceptions." (PMID 32241267, 2020). "SEMA3B was found to play a pivotal tumour suppressor role in multiple cancers such as breast, gastric, and lung cancers." (PMID 32241267, 2020). "In agreement with this study, we also noticed similar tendencies of SEMA3B, SEMA3G, SEMA3D and VEGFA mRNA level associations with patient survival and tumor malignancy grade." (PMID 33036421, 2020). "In contrast, the upregulated DEGs included both caner-drivers/oncogenes, e.g. FGFR1 and MAP3K8, and tumor suppressors, e.g. SEMA3B and BTG2." (PMID 30863497, 2019). "Sema3B upregulation achieved by the knockdown of regulatory miR-221 empowered the tumor-suppressor activity of this semaphorin in GBM, leading to the reduced migration and invasiveness of U87MG cells." (PMID 31052281, 2019). "All class-3 semaphorins can be cleaved by furin-like pro-protein convertases, which are overexpressed in tumor cells, resulting in an attenuation of their anti-angiogenic effects, as clearly demonstrated for Sema3B in breast and lung cancer models." (PMID 31052281, 2019). "Sema3A, Sema3B and Sema3F have been long considered inhibitors of tumor growth and metastasis, even if it has been reported that Sema3E inhibits tumor growth but promotes metastasis." (PMID 30454024, 2018). "Sema3B acts as a tumor suppressor in lung cancer and inhibits the formation of endothelial cells tubes in an in vitro angiogenesis; however, this function was abrogated upon mutation at the furin cleavage site." (PMID 30304095, 2018). "SEMA3B and SEMA3F have been implicated in mediating tumor-suppressing effects, whereas VEGFA has been shown to promote tumor cell proliferation and survival by binding to NRP127–33." (PMID 29018205, 2017). "Another gene differentially expressed (up), and also involved in tumour suppression was semaphorin 3B (SEMA3B)." (PMID 27448656, 2016). "In this case, we assumed that the expression of SEMA3B suppressed tumor growth in vivo, likely by the induction of apoptosis." (PMID 25961819, 2015). "SEMA3B induces apoptosis and the production of interleukin 8 by tumor cells by initiating the p38-mitogen-activated protein kinase pathway." (PMID 25961819, 2015). "SEMA3B-expressing tumours exhibited notable defects of pericyte recruitment to blood vessels compared with control xenografts." (PMID 25598217, 2015). "In the fifth—dox mouse active tumor growth (yellow line) began one week later compared to the control (blue line), in spite of the presence of SEMA3B in the construct." (PMID 25961819, 2015). "Some of these genes, e.g., RASSF1, NPRL2, and SEMA3B, suppress the growth of tumor cells in vitro and in vivo." (PMID 25961819, 2015). "The objective of our study was to expand our knowledge of the SEMA3B gene as a tumor suppressor and the mechanisms of its inactivation." (PMID 25961819, 2015).
tumor (continued). "An understanding of the role of SEMA3s, including SEMA3B, in carcinogenesis will help to use their tumor suppressive and anti-angiogenic properties for the development of new agents for cancer therapy in future." (PMID 25961819, 2015). "The objective of our study was to elucidate the distinct roles of SEMA3B in tumor suppression, particularly in apoptosis and angiogenesis." (PMID 25961819, 2015). "Important evidence of tumor suppressor activity includes the identification of cell regulatory pathways and other mechanisms that are affected by SEMA3B." (PMID 25961819, 2015). "Correlations between the methylation frequencies of the promoter and the intronic CpG-islands of SEMA3B with tumor stage and grade have been revealed for SCC, ADC and ccRCC." (PMID 25961819, 2015). "Class 3 semaphorins, Sema3B and Sema3F, are secreted proteins that regulate angiogenesis, tumor growth, and metastasis by binding to their transmembrane receptor complex consisting of plexins and neuropilins." (PMID 24065959, 2013). "Patterns of gene expression associated with the 2,656-tumor dataset were found in both TCGA datasets, including the low PC4a gene expression signature of high VEGFA and low SEMA3B, SEMA3C, SEMA3F, and PLXNB1." (PMID 23667446, 2013). "Sema3B and sema3F were previously characterized as tumor suppressors and as inhibitors of tumor angiogenesis." (PMID 18818766, 2008). "Many tumor suppressorcandidate genes such as CACNA2D2, DLC1, FUS1, H37, HYAL1, RASSF1A, SEMA3B, andSEMA3F and tumor susceptibility genes such as hMLH1 have been isolated from theregion." (PMID 18288251, 2007). "Overexpression of Sema3B could significantly inhibit the proliferation, invasion, and migration of CFPAC-1 and PANC-1 cells, which means that Sema3B may have an essential role in inhibiting tumor genesis and development in PC." (PMID 36713527, 2022). "Therefore, it was concluded that VEGF165 was produced by tumor cells and was used as a surviving factor, and SEMA3B has tumor-suppressing effects by blocking this VEGF pathway." (PMID 35205681, 2022). "Semaphorin 3B is considered to be a tumor suppressor gene that induces apoptosis in tumor cells." (PMID 30972979, 2019). "While other semaphorins such as Sema3B and 3F are tumor suppressors, Sema4D promotes tumor growth." (PMID 29971044, 2018). "ZR30-mediated reactivation of tumor suppressor gene SEMA3B expression may provide a microenvironment which further suppresses tumor growth through its angiostatic function." (PMID 29290950, 2017). "In conclusion, our in vitro and in vivo results reveal the tumor suppressor role of SEMA3B, which could acts by inducing apoptosis or, possibly, inhibiting angiogenesis." (PMID 25961819, 2015). "Moreover, IL-8 activity is required to mediate the recruitment of TAMs and metastatic dissemination in SEMA3B-expressing tumours." (PMID 25598217, 2015). "The SEMA3B protein is an antagonist of receptors for neuropilins 1 and 2 (Np1 and Np2) that also act as receptors for several isoforms of vascular endothelial growth factor (VEGF), which is a general initiator of tumor angiogenesis, and thus SEMA3B suppresses vascular growth in tumors." (PMID 26197878, 2015). "Most importantly, SEMA3B regulates neuronal migration and acts as a tumor a suppressor gene." (PMID 26197878, 2015). "The use of a representative set of primary tumors allowed us to reveal the correlations between the methylation frequency of both the promoter and the intronic CpG-islands of SEMA3B with tumor stage and grade for histological types of NSCLC (SCC and ADC) and for ccRCC." (PMID 25961819, 2015). "Furthermore, it was found that the induction of apoptosis by SEMA3B in tumor cells was mediated by inactivation of the Akt signaling pathway." (PMID 25961819, 2015). "However, this cannot explain why sema3B turned out to be a very effective inhibitor of tumor development in the brain and a very poor inhibitor in the subcutaneous microenvironment." (PMID 22936999, 2012).